TNF (tumor necrosis factor)
Diseases named in the same sentence as TNF in open-access papers (continued):
Sharing a sentence is not in itself a finding about the gene and the disease.
Hepatic steatosis (continued). "Moreover, in a mice model of hepatic steatosis, changes in gut microbiota are associated with exacerbated hepatic steatosis and inflammation through portal influx of TLR4 and TLR9 agonists, leading to enhanced hepatic tumor-necrosis factor (TNF)-α expression that drives NASH progression." (PMID 36986052, 2023). "Meanwhile, in a non-alcoholic fatty liver experimental model, BAs restored the reduced glutathione, and diminished MDA levels and other inflammatory mediators as TNF-α, IL-6, cyclooxygenase 2, and inducible nitric oxide synthase in hepatic tissues." (PMID 36959348, 2023). "A study of whole‐body Alox15−/− mice under a HFD revealed a decrease in lymphocyte infiltration and pro‐inflammatory mRNA levels of TNFα and IFN‐γ, thereby protecting against hepatic steatosis." (PMID 36637998, 2023). "Hepatic steatosis and the resulting NAFLD can lead to additional chronic inflammation by secretion of inflammatory cytokines such as IL6, TNF-alpha, and leptin." (PMID 35407455, 2022). "EMPA mitigated the hepatic content of TNF-α, IL-6, and NFκB in a dose-dependent manner that aligns with previous in vitro and in vivo investigations, in which EMPA lessens hepatic steatosis." (PMID 36358524, 2022). "Here, we provide solid evidence that celecoxib reduces lipogenesis‐triggered hepatic steatosis in AKT‐transfected mice, accompanied by the suppression of hepatocellular inflammatory responses (TNF‐α, IL‐6 and IL‐1β)." (PMID 35713152, 2022). "Finally, CD8+ T cells and, most importantly, the hepatic steatosis-induced CXCR6+ subset, were associated with liver injury and potentiated the transition of NASH to HCC via the secretion of pro-inflammatory cytokines and direct hepatocyte killing in a tumor necrosis factor (TNF)-dependent manner." (PMID 36230573, 2022). "For example, pro-inflammatory cytokine tumor necrosis factor α (TNF-α) disturbed the metabolism of hepatic fatty acid, contributing to the pathogenesis of hepatic steatosis." (PMID 34884447, 2021). "A decrease of fatty liver index (FLI), serum AST and GGT, and TNF-α/IL-6 levels were observed in the treatment group." (PMID 35052726, 2021). "In contrast, another study demonstrated that a tumor necrosis factor ameliorates lipid accumulation and inflammation in hepatocytes with HFD-induced hepatic steatosis by inhibiting p38 MAPK activity." (PMID 34557866, 2021). "In addition, an accumulation of ectopic fat, including visceral obesity and fatty liver, leads to a dysfunction of the adipose tissue, with impaired production of adipocytokines, which, in turn, favor an increase in pro-inflammatory cytokines, such as tumor necrosis factor alpha (TNF-α)." (PMID 35052726, 2021). "Consistent with the lower ALT levels, less hepatic steatosis, and higher AMPK activity, POA treatment reduced hepatic levels of the pro-inflammatory cytokines MCP-1 and TNF-α compared with OA treatment, while IL-1β remained unchanged." (PMID 32738301, 2020). "TNF-α has been also reported to decrease the protein expression of another aquaglyceroporin, AQP9, in a hepatocyte model of fatty liver disease." (PMID 32512939, 2020). "Hepatic steatosis and serum level of ALT, AST, and TNF-α reduced significantly in both groups after 12 weeks of the study intervention." (PMID 31345163, 2019). "Accordingly, serum and hepatic levels of proinflammatory cytokines such as tumor-necrosis factor alpha (TNF-α) and monocyte-chemoattractant protein-1 (MCP-1) have been found to be increased in patients with both simple hepatic steatosis and NASH." (PMID 29410708, 2018). "In comparison with placebo, GC significantly increased Sirt1 and decreased hs-CRP, TNF-α, IL-6, ALT, and the degree of fatty liver (P < 0.05)." (PMID 30263038, 2018). "GC supplementation in obese NAFLD patients reduced inflammatory biomarkers (IL-6, TNF-α, and hs-CRP), ALT, and the degree of fatty liver and increased Sirt1 compared with placebo." (PMID 30263038, 2018).
Hepatic steatosis (continued). "PPAR-α agonists can mitigate alcoholic fatty liver by upregulating PPAR-α and insulin signaling pathways while downregulating SREBP-1 activity and suppressing TNF-α production." (PMID 29091708, 2017). "Wang further found that the injection of recombinant murine FGF21 reduces IL-6, TNF-α, and leptin mRNA levels in WAT of monosodium glutamate-induced obese rats, with the improvement of glucose tolerance, lipid metabolic spectrum, and hepatic steatosis." (PMID 27616737, 2016). "TNF-α and IL-1β, pro-inflammatory and lipogenic factors, play crucial roles in the pathogenesis of NAFLD/NASH (liver steatosis, necrosis, apoptosis and fibrosis)." (PMID 27483220, 2016). "IL-10 is one of the most important anti-inflammatory cytokines; it inhibits TNF-α and LPS in Kupffer cells, thereby ameliorating ALD and preventing liver steatosis." (PMID 25692549, 2015). "Gene expression of TNF-α and TNF receptor is increased in liver of patients with NASH compared to both normal liver and fatty liver, and expression is higher in those patients with more severe disease." (PMID 24358045, 2013). "Treatment with silibinin improved liver steatosis and inflammation and decreased NASH-induced lipid peroxidation, plasma insulin and TNF-α." (PMID 19884114, 2011). "Adipose tissues also produce proinflammatory cytokines such as tumor necrosis factor-alpha (TNF-α), whose levels are higher in MASH compared to hepatic steatosis, and interleukin-6 (IL-6), which promotes the development of HCC by inhibiting apoptosis and activating pro-oncogenic pathways." (PMID 40560451, 2025). "In addition, overexpressing IREB2 increased IL-1β, IL-6, and TNF-α, promoting HFD-induced metabolic disorders, hepatic steatosis, and inflammation." (PMID 39910919, 2025). "Outcomes measured at baseline and post-intervention included anthropometrics, liver enzymes, metabolic profile, hepatic steatosis (CAP score), inflammatory markers (TNF-α, MDA), antioxidant enzymes (SOD, CAT), and lifestyle behaviors (physical activity, sleep)." (PMID 40988029, 2025). "In addition to conventional metabolic indicators (ALT, AST, hepatic steatosis index), objective data from polysomnography (PSG) (AHI, blood oxygen saturation), and inflammatory markers (IL-6, TNF-α) will be integrated." (PMID 40140484, 2025). "In terms of non-invasive diagnosis, CXCL8 has been incorporated in a combined index termed “NAFLD discriminant score”, together with adiponectin, TNF-α, and visfatin, to distinguish NASH from hepatic steatosis with a sensitivity and specificity of 90% and 66%, respectively." (PMID 40794228, 2025). "Cinnamaldehyde and glycyrrhizic acid, key components of Linggui Zhugan Decoction (LGZG), have been shown to ameliorate HFD-induced hepatic steatosis by suppressing STING-TBK1 pathway activation in KCs and reducing the release of inflammatory cytokines such as IFN-β and TNF-α." (PMID 40098962, 2025). "Given these considerations, the primary objective of this study was to assess the comparative six-month effects of infliximab (an anti-TNF agent) or vedolizumab (an anti-integrin agent) versus no biologic therapy on presumed hepatic steatosis in IBD patients." (PMID 39598344, 2024). "Cichoric acid plays an important role in reducing hepatic steatosis, as it reduces the expression of lipogenic actors, such as SREBP-1c, DGAT1, FAS, and SCD-1, and also of inflammatory factors such as IL-6, IL-1b, NF-κB, and TNF-α." (PMID 39458995, 2024). "Additionally, intervention with Saccharomyces boulardii, a strain of probiotic yeast, improved hepatic steatosis in HFD-induced NAFLD rats and decreased the expression of TNF-α." (PMID 38666855, 2024). "Considering the high antioxidant potential of GSE and the role of inflammation and oxidative stress in NAFLD, GSE affects the severity of hepatic steatosis by reducing inflammatory factors such as hs-CRP, TNF-α, and oxidative stress (MDA), as well as increasing antioxidant enzymes (SOD and CAT)." (PMID 38755622, 2024).
Hepatic steatosis (continued). "Other studies also reported elevation of IL-6, but not TNFα and IL-1β, as a compensatory mechanism that prevents the development of hepatic steatosis at the early stage of NAFLD." (PMID 38590904, 2024). "Anti-TNF agents, including infliximab, which are particularly used in moderate-to-severe IBD, are hypothesized to alleviate inflammation and improve hepatic steatosis and inflammation." (PMID 39598344, 2024). "The results showed that α-NETA and α-NETA plus PD98059 improved hepatic steatosis but no impact on TNF-α level of liver homogenates, infers that there was no influence on the progression of steatosis to steatohepatitis." (PMID 36624417, 2023). "However, they induced dose–response protective and ameliorative effects on the degree of hepatic steatosis, liver damage, and circulatory levels of ALT, AST, GTT, TNF-α, FFAs, and IL-6." (PMID 38004149, 2023). "Although it has been suggested that IL‐10 in the liver can inhibit TNFα production and protect against hepatic steatosis during HFD, no improvement in insulin sensitivity has been found." (PMID 36637998, 2023). "TNF-α could induce SREBP1 expression, resulting in hepatic steatosis; IL-1β and IL-6 are involved in hepatic steatosis and inflammation, which causes hepatic disease." (PMID 35409071, 2022). "The results indicated that SA significantly reduced their body weight, hepatic steatosis, serum triglyceride (TG), alanine transaminase (ALT) and tumor necrosis factor α (TNF-α) levels and increased serum high-density lipoprotein-cholesterol (HDL-C) levels in comparison with HFD group (p < 0.05)." (PMID 36432531, 2022). "In addition, there is increasing evidence that TNFα/TNFR1-mediated pathways create a pleiotropic microenvironment that plays a critical role in inflammation in the liver, hepatic steatosis, and fibrogenesis and thus in NAFLD progression." (PMID 36172180, 2022). "Conversely, the newer biologic drugs do not seem to affect negatively liver steatosis and metabolic parameters, although a weight gain has been reported with the long-term use of some TNF-α antagonists." (PMID 35147926, 2022). "Results showed that the intervention group, compared to the control group, had a significant decrease in the grade of hepatic steatosis and serum levels of high-sensitivity C-reactive protein (hs-CRP), AST, gamma-glutamyl transpeptidase (GGT), and TNF-α (p < 0.05)." (PMID 34426744, 2021). "Inflammatory cytokines promote the progression of fatty liver to fatty hepatitis, and serum and liver TNF-α levels have been reported to increase in patients with nonalcoholic fatty liver disease." (PMID 35059139, 2021). "With respect to inhibiting the inflammatory response and oxidative stress, genistein was reported to ameliorate fatty liver in insulin-resistant rats by activating the antioxidant profile, decreasing IL6 and TNF-α concentrations and preventing oxidative damage." (PMID 33953784, 2021). "Loss of TKT in the liver increased apoptosis, reduced cell proliferation, decreased TNF-α, IL-6, and STAT3 levels, and alleviated DEN/HFD-induced hepatic steatosis and fibrosis, highlighting a key role for TKT in promoting genome instability during liver injury and tumor initiation." (PMID 32913470, 2020). "Furthermore, depletion of white adipose tissue messenger RNA levels of MCP-1, TNF-α, and IL-6; serum concentrations of TNF-α, IL-6, and MCP-1; macrophage infiltration in adipose tissue; and attenuation of liver steatosis were observed." (PMID 32318236, 2020). "Therefore, the preventive effect of curcumin on hepatic steatosis is mediated, at least in part, by inhibiting hepatic TLR4-MyD88/NF-κB pathway and the subsequent production of TNF-α and IL-1β." (PMID 31788011, 2019).
Hepatic steatosis (continued). "For example, dietary supplementation with whole walnuts resulted in a significant decrease in macrophage infiltration and suppression of pro-inflammatory gene expression (tumor necrosis factor; TNF-α, interleukin-6; IL-6 and IL-10) in a mouse model of high-fat diet (HFD)-induced fatty liver disease." (PMID 31137456, 2019). "However, in mice, TNF-α expression has been shown to enhance hepatic lipogenesis and blockage of its receptor (TNF-α R1) can prevent the development of alcoholic fatty liver." (PMID 26101535, 2015). "Thus, lower expression of hepatic TNFα and MCP-1 in Casp1-/- mice compared to wild-type mice on the high fat diet likely contributed to a decrease in high fat diet-induced hepatic steatosis." (PMID 23409132, 2013). "Studies in NAFLD patients revealed that n-3 LCPUFA administration decreased serum transaminases, TNF-α, soluble TNF receptor 1 and 2 levels, and oxidative stress markers, with improvement in hepatic steatosis, fibrosis, hepatocyte ballooning, and lobular inflammation in 85% of the patients." (PMID 23082120, 2012). "Mechanistically, MCT4 alleviated hepatic steatosis by regulating a group of hub genes such as Arg2, Olr1, Cd74, Mmp8, Irf7, Spp1, and Apoe, which in turn impacted multiple pathways involved in lipid metabolism and inflammatory response, such as PPAR, HIF-1, TNF, IL-17, PI3K-AKT, Wnt, and JAK-STAT." (PMID 40330148, 2025). "Additionally, elevated levels of chronic inflammation markers, such as interleukin-6 (IL-6) and tumor necrosis factor-alpha (TNF-α), along with reduced secretion of muscle-derived factors, may further contribute to hepatic steatosis and liver inflammation." (PMID 40433168, 2025). "However, one retrospective cross-sectional study indicated that IBD patients not receiving anti-TNF treatment had higher rates of hepatic steatosis (assessed through abdominal imaging) compared to those undergoing anti-TNF therapy." (PMID 39598344, 2024). "Clinical data have reinforced this concept, with patients with IBD on anti-TNF therapy exhibiting reduced hepatic steatosis markers compared to those not on biologics, suggesting that TNF inhibition might mitigate hepatic fat accumulation." (PMID 39598344, 2024). "CSF treatment improved the hepatic steatosis, intralobular inflammation, and balloon-like changes while decreasing the lipid deposition in HFD rats by decreasing the levels of TG, AST, and ALT and down-regulating the expression of TLR4, MyD88, NF-κB, TNF-α, IL-6, as well as IL-8." (PMID 37762063, 2023). "Although we speculated that TNF-α in the liver would play a pivotal role in the development of hepatic steatosis in our model, however, we have not measured anti-inflammatory cytokines in this study, and further studies are needed to clarify the mechanism." (PMID 33388967, 2021). "In these studies, TNF-α is only sufficient to increase hepatocyte steatosis in the presence of adipocytes, suggesting that TNF-α does not cause a direct increase in liver steatosis, but acts through modulation of adipokine secretion profiles and adipose lipolysis." (PMID 34162924, 2021). "As the inflammation in the hepatocytes is a critical transformation from simple liver steatosis to steatohepatitis, FAT10 and related TNFα/IFNγ changes via NFκB and/or STAT3 pathways could be the candidate molecular parameters for low-dose alcohol effects on alcoholic hepatitis." (PMID 32630199, 2020). "Clinical studies examining patients with hepatic steatosis or NASH found supplementation, twice daily, with L-TRP for 14 months result in decreased plasma LDL, TG, and gamma gluthamylo transpeptidase levels with a correlative decrease in plasma IL-1β, IL-6, and TNF." (PMID 31921154, 2019). "However, research demonstrating that TNFα is a necessary component in the etiology of bovine fatty liver is lacking." (PMID 29344353, 2018).
Hepatic steatosis (continued). "Taken together, these studies suggest that TNF may not be a critical mediator of inflammation in this experimental form of hepatic steatosis." (PMID 25887406, 2015). "Furthermore, TNF-α expression has been shown to increase in alcoholic fatty liver, whereas several evidence was previously reported that TNFR1 knockout almost completely blocks development of ethanol-induced fatty liver." (PMID 26101535, 2015). "Furthermore, in ob/ob mice, a model of hepatic steatosis, it has been shown that metformin reversed hepatomegaly, hepatic fat accumulation, and ALT abnormalities, by reducing hepatic tumor necrosis factor-α (TNF-α) expression." (PMID 22194737, 2012). "We prospectively evaluated whether hepatic steatosis (HS) and the presence of carotid plaques (CPs) impacts on achieving minimal disease activity (MDA) in psoriatic arthritis (PsA) patients starting tumor necrosis factor (TNF)-α blockers treatment." (PMID 23036698, 2012). "Similarly, a 12-week TRE-8 combined with lacto-ovo vegetarian (LOV) intervention improved hepatic steatosis (FLI, Fatty Liver Index), body weight, waist circumference, glycolipid-related indicators (insulin levels, TG, and HDL-C), liver enzyme levels (ALT and GGT), and inflammatory status (TNF-α)." (PMID 41601725, 2026). "Finally, the use of a cocktail of 14 probiotic strains, belonging to Lactobacillus + Lactococcus, Bifidobacterium, Propionibacterium, and Acetobacter genera, could improve hepatic steatosis, by reducing AST and GGT activity, as well as TNFα and IL-6 levels, in NAFLD patients." (PMID 36139402, 2022). "Taking into account that hepatic PLZF overexpression induces hepatic steatosis and PLZF plays a crucial role in the natural killer cell function, we hypothesized that overexpression of PLZF will increase the contents of intrahepatic pro-inflammatory cytokine TNFα and IL-6." (PMID 36438786, 2022). "Finally, we could not quantify inflammatory molecules (e.g., tumor necrosis factor-alpha, cytokines, adipokines...) released by epicardial fat which potentially could have helped to explain the relationship among fatty liver, EAT, and cardiovascular damage." (PMID 27627804, 2016). "Our findings demonstrate that inflammatory and metabolic stress pathways, including TNF, IL-6, IL-1β, and MAPK13 signaling, promote the progression of hepatic steatosis to MASH and fibrosis under KD at TN but not at RT." (PMID 40864559, 2025). "DHA suppressed acute ethanol-induced hepatic steatosis and downregulated the levels of stearoyl-CoA desaturase 1 (SCD) and inflammatory cytokines, such as TNF-α and IL-6, but did not affect reactive oxygen species production." (PMID 38791514, 2024). "Our group reported that in patients with HCV chronic hepatitis TNFα genotype modulates the activity of the cytokine pathway, influences insulin sensitivity and the severity of HCV chronic hepatitis, but not liver steatosis." (PMID 23394097, 2013). "TNFα neutralisation decreased c-Jun phosphorylation, but not ATF3 expression, after hepatectomy in HFD-induced severe hepatic steatosis, indicating that JNK-c-Jun signalling may have an insignificant effect on ATF3 induction in this model." (PMID 36690638, 2023). "We have previously shown that consuming 1.5 g curcumin in addition to lifestyle intervention did not change hepatic steatosis and fibrosis, lipid profile, glucose, insulin resistance, ALT, anthropometric indices, tumor necrosis-α (TNF-α), and nuclear factor-kappa B (NF-kB) activity." (PMID 35956400, 2022). "A recent study has proven the role of microbiota-derived TLR agonists in promoting hepatic steatosis without affecting fructose-1-phosphate and cytosolic acetyl-CoA, reinforcing the idea that endotoxin engages TLR4 to trigger tumor necrosis factor (TNF) production by liver macrophages." (PMID 34899679, 2021).